FOXM1 (forkhead box M1)
Diseases named in the same sentence as FOXM1 in open-access papers (continued):
Sharing a sentence is not in itself a finding about the gene and the disease.
tumor (continued). "In OC, members such as FOXA1, FOXM1, FOXP4, FOXQ1, and FOXR2 primarily exhibit oncogenic functions, whereas others like FOXO and FOXP1 are associated with tumor-suppressive effects." (PMID 40746724, 2025). "Our results showed that overexpression of FOXM1 in subcutaneous xenograft tumor model rescued the inhibition of growth observed upon WTAP deficiency in vivo." (PMID 40846737, 2025). "FOXM1 not only independently activates the transcription of tumor-related genes but also collaborates with other molecular pathways or transcription factors to enhance the phenotypic characteristics of tumor cells." (PMID 39781349, 2025). "Prominently, elevated levels of a variety of transcription factors linked with tumor progression, such as EGFR, FOXM1, STAT3, FGFR1, and GATA6, were identified in the high PANO subtype." (PMID 40918470, 2025). "In NSCLC, thiostrepton has been shown to reduce PD-L1 expression through the downregulation of FOXM1 and inhibit the proliferation of tumor cells." (PMID 39594778, 2024). "As shown inFigure 1A, FOXM1 expression was significantly greater in OS tumor tissues than in paracancerous tissues." (PMID 39086352, 2024). "Among patients undergoing radiation therapy, RhoB overexpression correlated with elevated FOXM1 levels, advanced tumor, local and distant metastasis, and independently predicted poor survival, irrespective of other clinical factors." (PMID 38355625, 2024). "We found that, even in the early stages of EMPD, most cases showed strong and abundant positive expression of FOXM1, and its positivity increased with tumor progression." (PMID 38374400, 2024). "Disrupting this FOXM1/Rb interaction alters the tumor microenvironment, reducing metastatic potential." (PMID 39594778, 2024). "FOXM1 facilitates tumor progression by inhibiting the infiltration of CD8+ T cells, a process mediated through the modulation of Th1 chemokine expression." (PMID 39415846, 2024). "The increased activity of FOXM1 in TNBC contributes to multiple aspects of tumor progression and therapy resistance." (PMID 38918225, 2024). "Overall, these data demonstrated that FOXM1 is required to sustain stem-like traits and tumor initiation capacity in OC cells." (PMID 38806454, 2024). "FOXM1 is also involved in regulating significant processes in tumor development and progression such as proliferation, migration, angiogenesis, and chemoresistance 46–49." (PMID 38374400, 2024). "FOXM1-positive cells increased in number with tumor progression; early lesions had fewer positive cells, while metastatic lesions had more of them (*p < 0.05 and ***p < 0.001)." (PMID 38374400, 2024). "While the future goal is to translate FOXM1 inhibitors to clinical trials, potential synergistic drug combinations can maximize anti-tumor efficacy while minimizing off-target side effects." (PMID 38398147, 2024). "In contrast, the overexpression of SPDEF leads to a reduction in mRNA and protein levels of TF Foxm1, leading to tumor proliferation." (PMID 38674385, 2024). "The oncogenic role of FOXM1 in inducing cell proliferation, motility, invasion, and tumor growth in TNBC tumor models has been established." (PMID 39834541, 2024). "We found that FOXA1 and FOXM1 were significantly positively correlated with tumor purity in patients with BRCA, while FOXC2, FOXO3, FOXP1, and FOXQ1 were significantly negatively correlated with tumor purity in patients with BRCA." (PMID 38608123, 2024). "In mouse models with H1299 and PC9 tumor cells, thiostrepton treatment led to decreased tumor size and inhibition of FOXM1 and PD-L1 expression in tumor xenografts." (PMID 39594778, 2024).
tumor (continued). "In the molecular pathogenesis of EAC, the transcription factor FOXM1 plays a crucial role in promoting tumor growth." (PMID 39415846, 2024). "Here, we show that ABL1, a nonreceptor tyrosine kinase, contributes to the high expression of FOXM1 and FOXM1-dependent tumor development." (PMID 39060421, 2024). "Using EAC patient-derived organoid models and cell lines, we showed that FOXM1 regulates cellular proliferation, colony formation, and tumor growth in vivo." (PMID 38373993, 2024). "FOXM1 plays a critical role in cellular proliferation and tumor growth in EAC patient-derived organoids and cell line models." (PMID 38373993, 2024). "We have elucidated the role of FOXM1 in regulating cellular proliferation and tumor growth in EAC patient-derived organoids and cell lines and identified ERBB2 signaling as an upstream regulator of FOXM1." (PMID 38373993, 2024). "Inhibition of FOXM1 using thiostrepton also reduced tumor cell viability in a dose-dependent manner." (PMID 38374400, 2024). "In lung adenocarcinoma, phosphorylated FOXM1 was shown to recruit monocytes and promote M2 macrophage polarization when tumor cells were co-cultured with macrophages." (PMID 39347707, 2024). "It is plausible that the overexpression of FOXM1 is associated with copy number gains, resulting in the upregulation of cell CIN phenotype-related genes and tumor progression." (PMID 39594773, 2024). "Immunohistochemistry of 112 primary and 17 metastatic EMPD samples revealed that FOXM1 expression increased with tumor progression." (PMID 38374400, 2024). "FOXM1 inhibitors combined with immunotherapy like PD-1 inhibitors synergistically increase tumor apoptosis with tolerated immune-related side effects in syngeneic mouse models." (PMID 38398147, 2024). "We selected 4 candidate genes (PCSK9, SGPP1, PGK1 and FOXM1) reported to be closely involved in tumour progression and radioresistance for further analysis." (PMID 39548064, 2024). "Based on data linking FOXM1 to tumor stem cell phenotypes, we examined the impact of NB compounds on this phenotype in four HGSOC cell lines: CAOV3, OVCAR4, OVCAR5, and OVCAR8." (PMID 38704607, 2024). "ELDA calculation was based on the number of mice with palpable tumors at 21 days after the injection, which revealed that FOXM1 knockdown reduced the frequency of tumor-initiating cells by 4.6 times." (PMID 38806454, 2024). "In animal tumor models, targeting of FOXM1 by genetic or pharmacologic (i.e., small molecule) inhibitors demonstrated that FOXM1 is an important driver of tumor growth and progression in aggressive solid cancers." (PMID 39594778, 2024). "miR-509-3p overexpression significantly reduced the size and weight of subcutaneous tumors, increased tumor necrosis, reduced Ki67 and FOXM1 levels, and significantly increased apoptosis." (PMID 39319839, 2024). "The transcription factor FOXM1, which plays critical roles in cell cycle progression and tumorigenesis, is highly expressed in rapidly proliferating cells and various tumor tissues, and high FOXM1 expression is related to a poor prognosis." (PMID 39060421, 2024). "Although parental tumor was highly sensitive to TKI treatments, the FOXM1 + sgFOXA1 tumor exhibited strong TKI resistance, with 80% (4/5) tumors showing 60%–90% volume increase upon drug treatments." (PMID 39687207, 2024). "We demonstrated that miR-34a acts as a tumor suppressor in TNBC by suppressing the FOXM1/eEF2K oncogenic axis." (PMID 39594778, 2024). "On the other hand, it is known that HIF-1 transcriptionally activates FOXM1 expression, and FOXM1 transcriptionally activates tumor angiogenesis through the upregulation of vascular endothelial growth factor (VEGF) and its receptor, VEGFR2." (PMID 38398147, 2024). "Both FOXM1 and BIRC5 are implicated in driving tumour progression by increasing the cell proliferation rates." (PMID 38786043, 2024).
tumor (continued). "Genetic targeting of FOXM1 by RNAi-based strategies have been shown to suppress TNBC tumor growth in mice, suggesting it as a promising candidate for targeted therapies in TNBC." (PMID 38918225, 2024). "We first analyzed the expression of FOXM1 in the tumor tissues of OS patients by immunohistochemistry." (PMID 39086352, 2024). "In cholangiocarcinoma, FOXM1 promoted FoxP3+ Treg cell tumor infiltration, thereby suppressing CD8+ T cell activity." (PMID 39347707, 2024). "Patients in whom FOXM1 was expressed in more than 10% of tumor cells had significantly shorter disease-specific survival than the other patients (p = 0.0397)." (PMID 38374400, 2024). "Taken together, these findings in tumor cells suggest that ABL1-mediated FOXM1 phosphorylation and stabilization contribute to tumor development by promoting cell proliferation and suppressing tumor cell apoptosis." (PMID 39060421, 2024). "The FOXM1_Pathway in PID is a predefined collection of the FOXM1 transcription factor network that is involved in cell cycle regulation and DNA damage repair, and it promotes tumor cell proliferation." (PMID 38697979, 2024). "The avenue where FOXM1 inhibitors can be utilized is only expanding with additional research emerging and highlighting the unique role of FOXM1 in different aspects of tumor development and progression." (PMID 38398147, 2024). "FOXM1 expression increased with tumor progression in patients’ clinical samples, and high FOXM1 expression in primary tumors was significantly associated with shorter disease-specific survival." (PMID 38374400, 2024). "For instance, our study showed that the overexpression of NUAK1, LRRC17, FOXM1, and CDC20 as well as the downregulation of FLRT2 are associated with DNA repair pathway as well as tumor invasion pathways." (PMID 39149564, 2024). "In this study, we investigated FOXM1 expression and its role in tumor proliferation and development in EMPD patients’ clinical samples and in this cell line." (PMID 38374400, 2024). "The level of cell proliferation-associated genes, FOXM1 and BIRC5 genes, was expressed less in the miR-18a/low tumours (p < 0.05)." (PMID 38786043, 2024). "To understand how FOXM1 inhibits T cell tumor-infiltration, we focused our attention on antigen processing and presentation, as well as Th1 chemokines, which play dominating roles in T cell trafficking and recruitment." (PMID 38373993, 2024). "Pharmacological inhibition FOXM1—a gene within the ROS-related signature—proved effective in curbing tumor growth and boosting immunotherapy response in the LLC mouse model." (PMID 38577601, 2024). "It has been found that FOXM1 promotes the invasiveness of LUAD and the M2‐like polarization of tumor‐associated macrophages for LUAD immune escape." (PMID 38967523, 2024). "The pathological structure of tumor tissue improved, and Ki67, FOXM1, p-p38, and p-MK2 levels decreased, further proving that miR-509-3p inhibits GC progression by regulating FOXM1-mediated p38/MK2 pathway activation." (PMID 39319839, 2024). "CDK4/6 also phosphorylates and activates the transcription factor FOXM1, further promoting cell proliferation and tumor development." (PMID 38890443, 2024). "We found that the FOXM1 + sgFOXA1 PDX tumor displayed an upregulation of squamous markers and downregulation of adenomatous markers." (PMID 39687207, 2024). "FOXM1 is a classical transcription factor that promotes tumor metastasis, cell proliferation, differentiation, and invasion." (PMID 39319839, 2024). "MELK and FOXM1 were found to be the predominant activators of EZH2 transcription in these tumor stem cells, and MELK–FOXM1–EZH2 signaling mediated cellular resistance to irradiation." (PMID 37686402, 2023). "The transcription factor forkhead box protein M1 (FOXM1) has been suggested to promote tumor formation by regulating cell cycle." (PMID 37777749, 2023).
tumor (continued). "We found that the risk features of HMGA1 and FOXM1 in LUAD were closely related to patients’ gender, tumor stage and T classification, while HMGA1 was also correlated with N classification (p < 0.05)." (PMID 37240870, 2023). "Characterization of the different FOXM1 isoforms has revealed that in both normal and tumor tissues, FOXM1a has the lowest expression while FOXM1c has the highest expression." (PMID 37174744, 2023). "Loss of AhR enhanced stem cell and tumor growth and in the AOM/DSS model AhR-dependent suppression of FOXM1 and downstream genes was important for AhR-dependent anticancer activity." (PMID 38651159, 2023). "Using genetic approaches and small molecules that destabilize the FOXM1 protein, we found that targeting this mechanism induced G2/M cell-cycle arrest and apoptosis, blocked tumor progression, and impaired metastasis." (PMID 36795481, 2023). "Significant correlations emerged between FOXM1 expression and variables such as age, pathologic stage, tumor grade, vascular invasion, hepatic inflammation, and AFP levels." (PMID 37817774, 2023). "FOXM1 is an oncogenic transcription factor responsible for cell cycle regulation, tumor growth, proliferation, invasion, and metastasis." (PMID 37025658, 2023). "Third, FOXM1 mediates tumor cell resistance to irradiation, chemotherapies, and targeted therapeutics, including PI3K inhibitors, EGFR inhibitors, and CDK4/6 inhibitors, among others." (PMID 37686402, 2023). "While silencing endogenous FOXM1 impaired cell-cycle progression and tumor spheroid size in 3D conditions mimicking the organoid assays, these phenotypes were also rescued by expression of WT FOXM1." (PMID 36795481, 2023). "The interaction between FOXM1 and molecular pathways driving tumor growth, metastasis, and treatment resistance provide clear paths for rational design of drug combinations with FOXM1 inhibitors." (PMID 37370117, 2023). "Our findings underscored the significant differential expression of FOXM1 between tumor and adjacent tissues, reinforcing its potential role in HCC pathogenesis." (PMID 37817774, 2023). "FOXM1, as a crucial transcription factor, contributes to the phenotype of tumor cells by regulating downstream target genes." (PMID 36891298, 2023). "In the future, the therapeutic influence of specific inhibitors on CSCC tumor tissue genesis will be explored by analyzing the effect of USP39-specific acetylation on SIRT7/USP39/FOXM1 positive feedback axis." (PMID 37957720, 2023). "Subsequent multivariate analysis reaffirmed the independent prognostic relevance of FOXM1 (HR=1.843, 95%CI: 1.342-2.532, p<0.001), tumor stage, and residual tumor status." (PMID 37817774, 2023). "Here, we identify FOXM1 to be essential for the survival of tumor cells with MAD2 overexpression (OE) in mouse and human cell lines." (PMID 37452072, 2023). "Stable silencing of FOXM1 in established PyVmT cells severely impaired orthotopic tumor outgrowth and prevented lung metastasis, correlating with suppression of in vitro migration and invasion." (PMID 36795481, 2023). "Evidence has shown that FOXM1 is deeply involved in tumor progression, promotion, and the migration of PDAC." (PMID 36829815, 2023). "Altogether, combination treatment with low doses of vincristine and nanoparticle delivery of FOXM1 inhibitor RCM1 in a pre-clinical model of RMS has superior anti-tumor effects and decreases CHAC1 while reducing vincristine toxicity." (PMID 36816948, 2023). "Studies have also demonstrated that the FOXM1 transcription factor regulates VEGFA to promote tumor angiogenesis." (PMID 37081847, 2023). "TUNEL assay revealed the significant increase in apoptotic cell percentage in tumor tissues from the combination treatment group (73.53±4.24%) compared with FoxM1-shRNA only (32.34±3.60%) or IR only group (25.37±2.94%)." (PMID 36860922, 2023).
tumor (continued). "FOXM1 is highly involved in inflammation, and promotes tumor formation through direct activation of COX-2 and regulation of macrophage recruitment via its direct transcriptional target CX3CR1." (PMID 37370117, 2023). "Intriguingly, previous studies indicated that domatinostat reduced the expression of FOXM1 in pancreatic cancer and atypical teratoid/rhabdoid tumor cells." (PMID 37445993, 2023). "Increased expression of FOXM1 has been found to be capable of derailing proper anti-tumor immune responses through its direct binding to and subsequent upregulation of PD-L1." (PMID 37509358, 2023). "MiR-197, miR-374b, and miR-320 were also considered as the tumor suppressors that inhibited the CC cell proliferation and motility via FOXM1 suppression." (PMID 37689738, 2023). "It is worth mentioning that FOXM1 is significantly higher expressed in tumors than in normal tissues, and the expression increases with the increase of tumor stage." (PMID 37496990, 2023). "The SFKi dasatinib and eCF506 significantly attenuated tumor growth, downregulated FOXM1 expression, and induced gene expression changes consistent with FOXM1 inhibition in the luminal-like PDX." (PMID 36795481, 2023). "After selecting arterial phase CT, we chose 7 whole-tumor features and 3 features covering both the tumor and its surroundings to create WT and WP models for FOXM1 prediction." (PMID 37817774, 2023). "As FOXM1 potentially shapes the tumor immune landscape, understanding its expression can provide insights into a patient’s likely response to immune checkpoint inhibitors and other immunotherapeutic agents." (PMID 37817774, 2023). "Integrative transcriptome and m6A-seq analyses showed that ALKBH5 can demethylate the mRNA of the transcription factor FOXM1, thus leading to enhanced expression levels of FOXM1 and the recovery of tumor growth." (PMID 37007137, 2023). "Coexpression network analysis showed that FOXM1 participated in the tumor cell cycle and the infiltration of immune cells in EC." (PMID 37159818, 2023). "To understand the consequences of FOXM1 inhibition after long-term MAD2 expression, we used siRNA to knockdown Foxm1 in K and KM tumor cells." (PMID 37452072, 2023). "Several studies have demonstrated that FOXM1 cooperates with EZH2 to promote tumor growth, metastasis, and radioresistance." (PMID 37686402, 2023). "As with stable FOXM1 silencing, ablation of c-Src impaired proliferation in PyVmT cells and blocked cell-cycle progression and growth in 3D tumor spheroids." (PMID 36795481, 2023). "Thereafter, the changes in tumor weight and volume were analyzed and the results revealed that NAT10 silencing inhibited in vivo tumor growth, while this tendency was reversed by FOXM1 overexpression." (PMID 37948132, 2023). "FOXM1 expression demonstrated significant correlations with age, tumor stage, tumor grade, vascular invasion, hepatic inflammation, and AFP levels." (PMID 37817774, 2023). "This ‘pro-metastatic’ role of RB1 when bound to FOXM1 flies against the conventional view of RB1 as a tumor suppressor." (PMID 37686402, 2023). "Further, in the final stage of the experiment, mice were sacrificed and the protein expression level of IQGAP1 and FOXM1 in the excised tumor samples was analyzed using western blotting." (PMID 37202772, 2023). "Extensive investigation of the molecular mechanisms behind these clinical observations suggests that FOXM1 exerts multiple tumor promoting activities." (PMID 37370117, 2023). "FOXM1 has key functions in tumor development, invasion, and metastasis, such as lung, pancreatic, as well as breast cancer." (PMID 37159818, 2023). "Our data also suggest that miR-1 mediated CXCR4 modulations require FOXM1 pathway activity to promote tumor growth and metastasis." (PMID 36597126, 2023). "Comparatively, the risk characteristics of HMGA1 and FOXM1 in LIHC were correlated with patients’ grade, tumor stage and T classification (p < 0.05)." (PMID 37240870, 2023).